MALAT1 (metastasis associated lung adenocarcinoma transcript 1)
Diseases named in the same sentence as MALAT1 in open-access papers (continued):
Sharing a sentence is not in itself a finding about the gene and the disease.
cancer (continued). "Therefore, we tried to further uncover the role of MALAT1 in cancer cell viability under metformin treatment." (PMID 34164906, 2021). "MALAT1 (also known as NEAT2) is an evolutionary conserved lncRNA overexpressed in human cancers." (PMID 34204094, 2021). "Moreover, we observed that MALAT1 was weakly expressed in the subcutaneous WAT of CAC patients and was associated with poor prognosis in cancer patients." (PMID 33691715, 2021). "Our results allow us to better understand the different roles of MALAT1 in different cancers." (PMID 34308750, 2021). "Convincing evidence indicated that MALAT1 was an oncogene in various types of cancer." (PMID 34222668, 2021). "Interestingly, although studies have deemed MALAT1 as an oncogene across many cancer types, our results indicated that it was downregulated in HNC." (PMID 34733782, 2021). "The roles of MALAT1 in normal cell function and in cancer have been covered in detail elsewhere." (PMID 34940760, 2021). "MALAT1 expression was closely related to prognosis among different cancer patients." (PMID 34308750, 2021). "As functions of MALAT1 lncRNA differ among cancer types, this might imply that specific final effects may depend on specific molecular interactions." (PMID 35011635, 2021). "Moreover, its role in cancer is likely context-dependent since MALAT1 is shown to have anti-metastatic effects in breast cancer." (PMID 33803619, 2021). "Accumulating evidence indicates that their dysregulation in the human genome contributes to the development of human hematologic or solid malignancies, such as XIST, HOX antisense intergenic RNA (HOTAIR), and Metastasis Associated Lung Adenocarcinoma Transcript 1 (MALAT1)." (PMID 34692550, 2021). "MALAT1 also regulates MMPs expression and cell invasiveness in cancer cells." (PMID 32317757, 2020). "MALAT1 was found to have a function in the development of cancer correlated with miRNAs." (PMID 31792655, 2020). "Further, small molecules specifically targeting the MALAT1 triple helix structure have been identified and they lay the foundation for new classes of anticancer therapeutics for the treatment and investigation of MALAT1-driven cancers." (PMID 32503170, 2020). "MALAT1 and NF-κB signaling crosstalk during cancer and other diseases." (PMID 32867128, 2020). "MALAT1 deregulation has since then been noted in several human cancers." (PMID 32050583, 2020). "In conclusion, we revealed the essential role of exosomes in communication between cancer cells and demonstrated that MALAT1 expression in exosomes was required for inducing aggressiveness phenotype by regulating FUT4-associated fucosylation and PI3K/Akt/mTOR pathway." (PMID 32209115, 2020). "MALAT1, located on chromosome 11q13.1, is dysregulated in many cancers." (PMID 33330574, 2020). "As a highly conserved lncRNA in mammals, MALAT1 played an important role in cancer." (PMID 32238151, 2020). "In OSCC, MALAT1 is also reported to play oncogenic roles in EMT-related cancer metastasis." (PMID 33123473, 2020). "MALAT1 further sponged miR-26a-5p, thereby disrupting the cancer-suppressive effect of miR-26a-5p." (PMID 32453410, 2020). "Additionally, MALAT1 binds a number of miRNAs and functions as a ceRNA, and thereby regulates the expression of miRNA target mRNAs and proteins, cancer cell proliferation, migration, invasion, and metastasis." (PMID 32174966, 2020). "Aberrant expression and localization of hnRNPK, commonly observed in cancer, could thus also play a role in the change of MALAT1 localization in HCC." (PMID 32340118, 2020). "A previous study has confirmed that MALAT1 might alter growth and colony formation of cancer cells in vitro." (PMID 31792655, 2020). "MALAT1 has also been shown to promote cancer through functioning as a ceRNA." (PMID 32174966, 2020). "Based on the available evidence for aberrant expression of MALAT1 in cancer, we hypothesized that dysregulation of MALAT1 plays an important role in the pathogenesis of primary GB." (PMID 31479414, 2020).
cancer (continued). "CRISPR/Cas9 silencing of NEAT1 or MALAT1 was reported to inhibit metastasis of cancer cells." (PMID 33330574, 2020). "Upregulation of MALAT1 has been found in various cancers and more recently in ESCC." (PMID 33123280, 2020). "It is clear, however, that different RBPs, like HuR and GRSF1, must play a central role in this process and that deregulations in this network of RBPs are responsible for the aberrant localization of lncRNAs in cancer, as observed for MALAT1 and lncCyt b in HCC." (PMID 32340118, 2020). "For example, lncRNA MALAT1 is upregulated in various cancers." (PMID 32802874, 2020). "Recently, dysregulation of MALAT1 was discovered among many other cancers." (PMID 33344634, 2020). "Taken together, MALAT1 has been shown to be an important player in cancer biology." (PMID 32369931, 2020). "Therapeutics targeting Malat1 may have anti-cancer properties through induction of TDP-43 toxicity and an innate immune response induced by increased dsRNA levels." (PMID 31863590, 2020). "Furthermore, the dual roles of MALAT1 in cancer progression have been suggested by studies using Malat1 knockout (KO) mice." (PMID 32486413, 2020). "MALAT1 is frequently upregulated in HCC and is associated with cancer metastasis and recurrence." (PMID 32872482, 2020). "Further correlationanalysis demonstrated that high MALAT1 expression waspositively related to large tumor size, poor histologicalgrade, terminal stage of cancer and tumor metastasis.Knockdown of MALAT1 inhibited A549 cell growthand invasion, as well as the expression of MMP2 andMMP9." (PMID 31863664, 2020). "Interestingly, accumulating evidence suggests that MALAT1 plays an important role in numerous diseases including cancer." (PMID 32503170, 2020). "Among lncRNAs, MALAT1 is probably the best characterized in cancer biology." (PMID 33375130, 2020). "The oncogenic role of MALAT1 in the progression of human cancers has gradually emerged." (PMID 31953613, 2020). "Therefore, targeting MALAT1 will be a promising therapeutic target for inhibiting fusion protein-driven cancer progression." (PMID 32703936, 2020). "The findings in this study showed that MALAT1 may be a potential therapeutic target for the treatment of fusion protein-driven cancers, and validation in additional clinical patients is needed in further studies." (PMID 32703936, 2020). "In addition, MALAT1 overexpression increases the metastasis potential of cancer cells and is involved in the pathogenesis of various human diseases, involved in the onset and development of various tumors or tumor suppressor pathways." (PMID 33213097, 2020). "Among them, many well-known cancer relevant genes such as MALAT1 and PVT1 were included." (PMID 33318305, 2020). "The inconsistent effect of MALAT1 on cell proliferation calls for caution when considering MALAT1 for anti-cancer therapy, as although its downregulation may prevent EMT, it can promote invasion plasticity of individually migrating cells." (PMID 32369931, 2020). "The Cers2 gene plays a role in the regulation of cell growth, BCL2 encodes an outer mitochondrial membrane protein that can block apoptosis in cancer cells, PTEN is a tumor suppressor that can be mutated in cancer cells, and MALAT1 is a noncoding RNA that is highly expressed in the nucleus." (PMID 31618108, 2020). "The mechanism by which MALAT1 contributes to cancer progression is through induction of EMT." (PMID 33123280, 2020). "MALAT1 may act as a transcriptional regulator for numerous genes, including some genes involved in cancer metastasis and cell migration, and it is involved in cell cycle regulation." (PMID 32342982, 2020). "Although various functions have been described for MALAT1 in many different cancers, the mechanism by which MALAT1 regulates EMT in ESCC remains unclear." (PMID 33123280, 2020). "Hence, MALAT‐1 was extrapolated to improve drug‐tolerance of LSCC cells through repressing apoptosis of cancer cells." (PMID 31837057, 2020).
cancer (continued). "In many of these studies MALAT1 knockdown affected transcription and/or pre-mRNA splicing of critical genes involved in migration and cell adhesion in addition to genes involved in critical cancer pathways." (PMID 32503170, 2020). "Further investigations along this line are warranted in order to understand the role of MALAT1 in the development of the drug resistance phenotype in cancers and to identify potential combinatorial therapeutic opportunities to target MALAT1 to augment chemotherapeutic response." (PMID 32503170, 2020). "MALAT1 is a lncRNA, which has been reported to be deregulated in different types of cancer." (PMID 32462404, 2020). "In various cancers, the expression of MALAT1 is usually upregulated." (PMID 31304004, 2019). "Furthermore, MALAT1 was reported to be closely related to the development and progression of a variety of human cancers." (PMID 31250518, 2019). "The role described for MALAT1 is dependent on the cancer types and the experimental model systems." (PMID 30781877, 2019). "A recent study has indicated that lncRNA interactions with miRNA and mRNA—such as H19, MALAT1, and KCNQ1OT1, HULC, and HOTAIR—could be potential diagnostic and prognostic biomarkers in cancer." (PMID 31164794, 2019). "Also, increasing reports have indicated that Malat1 activates autophagy and participates in tumorigenesis, such as cell proliferation, apoptosis and metastasis, in a number of cancer cells." (PMID 31372165, 2019). "Former studies illustrated that lncRNA could regulate certain gene expressions in human cancers, and SOX9 has been revealed to be regulated in several lncRNA in cancers such as lncRNA MALAT1 and SNHG1." (PMID 31402556, 2019). "The reported “circulating miRNAs” and plasma lncRNAs or lncRNAs such as HOTAIR, metastasis-associated lung adenocarcinoma transcript 1 (MALAT1), H19, and GAS5 might also have value in the evaluation of radioresistance in cancer patients." (PMID 31174564, 2019). "MALAT1 has been reported to bind PRC2 complex in cancer cells." (PMID 30788509, 2019). "Dysregulation of H19, HOTAIR, and MALAT1 was observed in many types of cancer." (PMID 31827510, 2019). "Among the lncRNAs selected above, Malat1 has been the most extensively studied in many cancers and may have autophagy-promoting effects." (PMID 31425535, 2019). "Notably, different or opposite phenotypes resulting from different strategies for inactivating MALAT1 have been observed, which led to distinct models for MALAT1’s functions and mechanisms of action in cancer and metastasis." (PMID 30781877, 2019). "MALAT1 expression has been shown to be either upregulated or downregulated in human cancers." (PMID 30781877, 2019). "We therefore wanted to know whether similar mechanisms were relevant in the context of MALAT1 and its contributions to cancer development." (PMID 31777593, 2019). "However, the role of MALAT1 in regulating cancer stemness and post-translational modifications needs to be further studied." (PMID 31480503, 2019). "It remains to be determined whether MALAT1 suppresses metastasis by inactivating TEAD in other cancer types." (PMID 30781877, 2019). "Additionally, lncRNA MALAT-1 can also serve as a cancer biomarker owing to its ability to facilitate cell proliferation and migration." (PMID 31350456, 2019). "MALAT1 was reported to act as an endogenous sponge of several RNAs in cancers." (PMID 30683807, 2019). "Thus, finding the putative m6A5044 structural switch to modulate miRNA-binding site accessibility in MALAT1 represents an intriguing mechanism to search in other modified RNAs as well as a novel biomarker and anti-cancer drug target." (PMID 31717552, 2019). "Nuclear paraspeckle assembly transcript 1 (NEAT1) and metastasis-associated lung adenocarcinoma transcript 1 (MALAT1), also known as Nuclear-Enriched Abundant Transcript 2 (NEAT2) were among the first lncRNAs to be implicated in progression and metastasization of cancers." (PMID 31003545, 2019).
cancer (continued). "MALAT1 is upregulated in several cancer types and acts as a pro-proliferative gene." (PMID 31141943, 2019). "MALAT1 is probably the best-characterized lncRNAs in cancer biology." (PMID 31191327, 2019). "In addition to the Hippo-YAP pathway, MALAT1 has been reported to regulate other signaling pathways in cancer, including PI3K-AKT, MAPK, WNT, and NF-κB pathways." (PMID 30781877, 2019). "However, more high-quality larger-scale studies across ethnicities are warranted to explore the prognostic value and carcinogenic function of MALAT1 before it is applied to the treatment and management of cancer." (PMID 30093838, 2018). "Hence, we preliminarily considered that MALAT1 was possibly a common marker for prognosis of both types of cancer." (PMID 29416769, 2018). "Reports on MALAT1 have largely highlighted its oncogenic roles in various cancers." (PMID 29702599, 2018). "Inhibition of MALAT1 suppressed cancer cells proliferation and invasion." (PMID 29374143, 2018). "The downregulation of MALAT1 may achieve similar effects, so E2 would impact cancer cells when the level of MALAT1 is decreased." (PMID 30459529, 2018). "MALAT1 overexpression was first described in cancer and in response to 24 h hypoxic stimulus." (PMID 30456215, 2018). "MALAT1 is an established oncogenic lncRNA, which plays an important role in many cancers." (PMID 30131454, 2018). "One of the most widely studied lncRNAs in cancer biology, MALAT1, could regulate the expression of many tumor-related genes through interaction with different protein complexes." (PMID 29511340, 2018). "In cancers, the expression of MALAT1 is upregulated by hypoxia or HIF-1α79,80." (PMID 29449542, 2018). "Therefore, we combined the published studies to evaluate the prognostic and clinical value of MALAT1 among different types of cancer." (PMID 30093838, 2018). "The abundance of the selected mRNAs with various expression levels, as well as enhancer-associated RNAs and cancer biomarker long non-coding RNAs (MALAT1, GAS5 and TUG1), were not significantly different between the two groups as assessed by RT-qPCR." (PMID 30140372, 2018). "Although HELA and MCF7 cells secrete MALAT1, these are cancer/tumor cells." (PMID 30263873, 2018). "In addition, our study was the first meta-analysis to show the significant association between the lncRNA ANRIL, MALAT1, HOTTIP, and HULC polymorphisms and cancer risk." (PMID 29802154, 2018). "In addition, cancer cells in the G2 phase increased in miR-145 inhibitor group and decreased in the si-MALAT1 group compared with the NC group (P < 0.05)." (PMID 30285605, 2018). "We were also able to show that MALAT1 is aberrantly expressed in TMAs of three cancer groups (colorectal, breast, and pancreatic), suggesting that lncRNA MALAT1 is associated with multiple cancers and its use as a therapeutic target should be investigated further." (PMID 30189670, 2018). "The analysis of small samples suggested that the expressions of MALAT1 could be negatively correlated to prognosis and survival, but positively related to both metastasis and relapse of both kinds of cancer." (PMID 29416769, 2018). "MALAT1 is the first characterized oncogenic lncRNA that promotes the progression of many cancers." (PMID 30154407, 2018). "Furthermore, given the growing importance of lncRNAs in cancer pathology, the involvement of MALAT1 should be exploited." (PMID 30319549, 2018). "Nevertheless, despite the recent emergence of these epigenetic roles for MALAT1 in cancer, the question of whether MALAT1 influences other epigenetic mediator proteins to regulate inflammation in DR still remains unanswered." (PMID 29695738, 2018).
cancer (continued). "Several cancer-related studies have revealed that MALAT1 is capable of binding to enhancer of zeste homolog 2 (EZH2), the main catalytic subunit of the histone methyltransferase polycomb repressive complex 2 (PRC2), and promotes oncogenesis by reprograming the chromatin state." (PMID 29695738, 2018). "Cancer related gene expression assay was done after transfection of siR- MALAT1." (PMID 28077118, 2017). "Further studies confirmed that MALAT1 is an independent prognostic factor in some cancers as well." (PMID 29246025, 2017). "It has been demonstrated that the long non-coding RNA MALAT1 may regulate many biological processes, including cancer development." (PMID 28077118, 2017). "Indeed, MALAT1 levels were found to be more abundant in radio-resistant than in radio-sensitive cancers." (PMID 29147648, 2017). "In cancer cell, nuclear MALAT1 is involved in proliferation, invasion and migration." (PMID 27732939, 2017). "For instance, MALAT1 could modulate cell proliferation, invasion and apoptosis in various types of cancers." (PMID 28697764, 2017). "We evaluated the characteristics of this optical imaging probe in vitro and determined whether it can be used for the imaging of MALAT1 expression in malignant tumours in vivo." (PMID 29156758, 2017). "RUNX1-IT1, MALAT1, H19, and HOTAIRM1 have been widely associated with cancer in recent years." (PMID 28389671, 2017). "Together our results indicate that MALAT1 may have additional functions in repressing tumor suppression to promote cancer progression." (PMID 29632545, 2017). "MALAT1 is reported to participate in the regulation of CSCs in various cancer types." (PMID 28872613, 2017). "As decreased proliferative capacity is frequently observed in the chemo-resistant cancer cells, our results suggests that the MALAT1-miR-203-TS pathway participates TMZ resistance may through influencing the proliferation of GBM cell." (PMID 28187000, 2017). "This is not a general phenomenon shared by all lincRNAs as MALAT1 is often associated with cancer progression but is only upregulated in a subset of the cancers where EINCR1 is overexpressed." (PMID 28732076, 2017). "Recently, Sp1 is found to transcriptionally activate MALAT1 expression through targeting the promoter region and the Sp1-MALAT1 axis may play a critical role in cancers." (PMID 28615056, 2017). "Moreover, we also selected five representative disease lncRNAs (HOTAIR, MALAT1, H19, MEG3 and TUG1) that play key roles as oncogenic molecules associated with various cancers to investigate their occurrences at the top 5%-20% of the candidate lists." (PMID 28076842, 2017). "Of special note, the close proximity of NEAT1 to MALAT1, and their similar roles as oncogenes in multiple cancers suggests that the entire locus may be subject to aberrant regulation in cancer." (PMID 29113413, 2017). "These cancers also shared three seed genes (H19, MALAT1 and MEG3)." (PMID 28051121, 2017). "MALAT1 is on COSMIC consensus cancer gene list and annotated as related with pediatric RCC." (PMID 28358873, 2017). "Collectively, elevated MALAT-1 could be developed as an auxiliary molecular marker to aid in cancer diagnosis." (PMID 29254244, 2017). "High MALAT1 expression levels in cancer promote cell proliferation, migration and invasion." (PMID 27802187, 2017). "Moreover, MALAT1, another noticeable lncRNA in cancer, is tightly co-expressed with NEAT1 in both pRCC and ccRCC (Spearman’s correlation; 0.79 and 0.87 respectively)." (PMID 28358873, 2017). "Our data may help to better understand the clinical value of elevated MALAT-1 in the diagnosis of various cancers." (PMID 29254244, 2017). "MALAT1 is one of several well-known lncRNAs involved in many cancers, and our microarray results showed significantly differential expression level in gastric adjacent normal and cancer tissues." (PMID 28077118, 2017).